STAT3 (signal transducer and activator of transcription 3)
Diseases named in the same sentence as STAT3 in open-access papers (continued):
Sharing a sentence is not in itself a finding about the gene and the disease.
Immunodeficiency (89 papers, 2011 to 2026). Failure of the immune system to protect the body adequately from infection, due to the absence or insufficiency of some component process or substance. "Beyond oncogenic roles, germline STAT3 variants are associated with immune disorders such as hyper‐IgE syndrome and autoimmune cytopenias, underscoring its dual contribution of STAT3 to both malignancy and immune regulation." (PMID 41527523, 2026). "There have been reported cases of patients with immunodeficiency and immunological dysregulation caused by loss-of-function or gain-of-function mutations in STAT3." (PMID 40059876, 2025). "Inherited severe immunodeficiencies, such as chronic granulomatous disease, STAT3 deficiency or SCID (severe combined immunodeficiency), can become predisposed to invasive pulmonary mold disease." (PMID 39852489, 2025). "Key motifs (e.g., GYXXQ of IL-10R1) mediate the STAT3 signaling pathway, whose mutations lead to immunodeficiency (e.g., IBD), confirming that coevolution of the ligand–receptor interaction interface is a core mechanism driving immune homeostasis." (PMID 41300695, 2025). "A study of primary immune deficiency cases involving disseminated coccidioidomycosis found two patients had STAT3 LOF mutations, one had IFN-γ receptor-1 deficiency, three had IL-12 receptor LOF mutations, and two had STAT1 GOF mutations." (PMID 41164159, 2025). "While both LOF and GOF of STAT3 cause immune deficiency, GOF leads to infections distinct from those observed with LOF, accompanied by more common connective tissue abnormalities." (PMID 38644452, 2024). "Overall, STAT3 DN mutations can lead to autosomal dominant HIES with a characteristic immunodeficiency triad of elevated IgE, cyst-forming pneumonia, and recurrent cold skin abscesses caused by deficient STAT3-mediated TH17 differentiation." (PMID 37140667, 2023). "This has been suggested to occur in patients with gain-of-function mutations of STAT3 who, surprisingly, show some immunodeficiencies." (PMID 37828541, 2023). "PGM3 deficiency has variable clinical features ranging from the phenotype of STAT3 deficiency to severe combined immune deficiency (SCID)." (PMID 36140582, 2022). "Our study detected nine pathogenic variants associated with the GOF of STAT-3 that have been described to be associated with an immunodeficiency phenotype." (PMID 35990641, 2022). "In the same way, other authors have related GOF mutations in STAT-3 with several immunodeficiency phenotypes, considering it as a candidate causative gene of the CVID phenotype." (PMID 35990641, 2022). "Given its critical role in immune homeostasis and the regulation of both innate and adaptive immunity, pathogenic variants in the STAT3 gene account for a variety of human conditions including immune deficiencies and cancer." (PMID 36292796, 2022). "Patients with clinically significant immunodeficiency and immune dysregulation resulting from loss-of-function or gain-of-function mutations in STAT3 have been described." (PMID 29472924, 2018). "Aberrant activation of STAT3 signaling pathway was linked to immune disorders and inflammatory response of monocytes or macrophages." (PMID 30326918, 2018). "The JAK/STAT and STAT3 signaling pathway interacts with various cytokines, with mutations in pathway genes associated with both autoimmune and immunodeficient diseases." (PMID 29335024, 2018). "This study identifies a novel immunodeficiency with phenotypic similarities to STAT3 hyper-IgE syndrome caused by loss of function of GP130." (PMID 28747427, 2017). "The cytotoxicity of NK and NKT cells is essential for eliminating abnormal cells and maintaining immune surveillance, the quantitative and functional alterations observed in these cells provide an explanation for the immunodeficiency associated with STAT3 mutations." (PMID 41212476, 2025).
Immunodeficiency (continued). "Recurrent infections are a hallmark of STAT3 DN hyper-IgE syndrome, a rare immunodeficiency syndrome, and our study suggests that neutrophil-avid nanocarriers have potential for directed delivery of cargo therapeutics to improve neutrophil infection clearance in these patients." (PMID 39134362, 2024). "In these patients, the excessive dimerisation of STAT3 and its consequent nuclear localisation will reduce mitoSTAT3, which may thereby cause the observed immune deficiencies due to compromised T cell function." (PMID 37828541, 2023). "STAT3 loss-of-function mutations have been reported in the human immunodeficiency condition termed Hyper immunoglobulin E syndrome; these patients are susceptible to bacterial and fungal infections as well as compromised T cell memory to varicella zoster virus and EBV." (PMID 36441748, 2022). "In addition to studies using cell-specific Stat3 deficient mice, the relevance of Stat3 in shaping the immune response has been further demonstrated by genetic human immunodeficiency and immune dysregulations caused by mutations in the Stat3 gene." (PMID 29866996, 2018). "In summary, we found that STAT3 influences the differentiation and function of NK and NKT cells by modulating CX3CR1, thereby providing an explanation for the immune deficiencies observed in patients with STAT3 mutations." (PMID 41212476, 2025). "Overall, our study revealed an increase in CX3CR1+CD57+ NK and NKT cells in patients with STAT3 mutation and identified the regulatory role of STAT3 in CX3CR1 expression, which explains the immune deficiency observed in these patients." (PMID 41212476, 2025). "Combined, these data strongly indicate that altered dynamics of STAT3 F408L dephosphorylation result in GOF for transcriptional activity and is likely the cause of immune disease in P1." (PMID 39836489, 2025). "Germline loss‐of‐function (LOF) variants in the STAT3 gene result in autosomal‐dominant hyperimmunoglobulin‐E syndrome (OMIM:147060) which is characterized by high serum IgE, eosinophilia, eczema, and immunodeficiency." (PMID 38404237, 2024). "The expressions of TNF and STAT3 were markedly up-regulated in the CY-induced immunodeficiency after a 14-day treatment with GAC (20 or 40 mg/kg) (p < 0.01)." (PMID 37853057, 2023). "The signal transducer and activator of transcription 3 (STAT3) is a transcription factor involved in inflammatory responses, immune disorders, and carcinogenesis." (PMID 37762522, 2023). "Both groups also had similar underlying immune dysfunction, with upregulation of immune processes such as “Interleukin-1 signaling” and “Interleukin-6/JAK/STAT3 signaling” throughout disease compared to healthy controls." (PMID 37090709, 2023). "The activation of STAT3 and NF-κB not only plays an important role in vitiligo, but also acts as an inflammation amplifier in many immune diseases." (PMID 37731844, 2023). "Germline STAT3 gain-of-function (GOF) mutations are associated with diverse clinical manifestations, including immunodeficiencies and autoimmune diseases." (PMID 35865518, 2022). "NF-κB and STAT3 signaling pathways regulate gene transcription to influence the pathological evolution of inflammatory and immune diseases." (PMID 36286060, 2022). "STAT3 activation can regulate a large number of downstream genes related to cell proliferation and immune diseases." (PMID 33122966, 2020). "As a key regulator of immune responses, abnormal Stat3 activity has been associated with immunodeficiency such as HIES in human and Crohn’s disease-like conditions in mouse Stat3 CKO." (PMID 28222105, 2017). "For example, mutations in IL2RA and IL7R cause immunodeficiency and mutation in TYK2 and STAT3 have been reported to cause hyper-IgE syndrome." (PMID 21552549, 2011).
Immunodeficiency (continued). "Additionally, we found that STAT3 mutations regulate the phenotype and function of immune cells by modulating CX3CR1 and IL-4, further elucidating the mechanisms of immune deficiency and high IgE levels in patients with STAT3 mutations." (PMID 41212476, 2025). "Combined immunodeficiencies alongside syndromic characteristics were associated with pathogenic mutations in DOCK8, STAT3, WAS, ATM, and TBX1, which included an autosomal dominant STAT3 variant (c.1144C>T; p.Arg382Trp) and an X-linked WAS variant (c.271C>T)." (PMID 40806973, 2025). "This suggests that conventional immune modulation with glucocorticoids or csDMARDs may precipitate immunodeficiency in STAT3-GOF." (PMID 39247195, 2024). "In this study, it was observed that GAC could increase the expression levels of TNF and STAT3 in mice with CY-induced immunodeficiency." (PMID 37853057, 2023). "STAT3 has been widely studied in the context of immune diseases and cancer." (PMID 38203559, 2023). "Since STAT3-HIES is a primary immunodeficiency, it could, in principle, be treated by allogeneic hematopoietic stem cell transplantation (HSCT)." (PMID 36292796, 2022). "Another two cases of Talaromyces marneffei mixed infection were confirmed to have atypical types of immunodeficiency after the occurrence of Talaromyces marneffei infection, one with STAT3 hyper-IgE syndrome and the other with anti-IFN-γ autoantibody-associated immunodeficiency syndrome." (PMID 35310841, 2022). "As STAT3-targeting approaches relieved inflammation, immune disorders, and organ failures in these mice, targeted intervention towards this pathway could suppress the lethal CRS inflammatory state." (PMID 34518653, 2022). "STAT3 has been considered as a potential target in a series of diseases, including cancer and immune disorders; therefore, we wondered whether STAT3 could be a suitable pharmacological target to regulate bone metabolism and bone homeostasis." (PMID 34824272, 2021). "Recent studies have found that this traditional Chinese medicine plays a vital role in macrophage infiltration and M2 polarization, as well as in regulating immune disorders, and it even regulates the transcription factors NF-κB and STAT3 to alter inflammation, tumorigenesis, and development." (PMID 32149121, 2020). "We focus on these kinds of events involved in JAK-STAT signal pathways, especially the ones triggered by aberrant activated STAT3, an oncoprotein which participates in essential processes of cell survival, growth and proliferation in many types of tumors, as well as immune diseases." (PMID 23704931, 2013). "Patients with germline monoallelic dominant negative or hypermorphic STAT3 variants, who present with immunodeficiency and/or immune dysregulation, have revealed the importance of balanced STAT3 signaling in lymphocyte differentiation and function, and immune homeostasis." (PMID 39836489, 2025). "PIDDs to consider in this context include hyper-IgE syndrome (STAT3 or DOCK8 deficiency), immune dysregulation, polyendocrinopathy, enteropathy, X-linked syndrome (IPEX syndrome), Omenn syndrome, Wiskott-Aldrich syndrome, and other rare combined immunodeficiencies." (PMID 40899446, 2025). "Similarly, other mutations such as Y640F in STAT1 or D661V in STAT3, which occur in the SH2 domain or in regions that regulate dimerization, have been reported to enhance STAT activity and are sometimes found in hematologic malignancies and immune disorders." (PMID 41438753, 2025). "In STAT3-HIES, immunodeficiency is primarily due to defective IL-6 signaling, which plays a crucial role in Th17 cell differentiation." (PMID 40491905, 2025). "Signal transducer and activator of transcription 3 (STAT3) is a transcription factor activated canonically by numerous cytokines and other factors, with significant roles in immunity, immune diseases, and cancer." (PMID 38203559, 2023).
Immunodeficiency (continued). "Serine/threonine phosphorylation of STAT1, STAT3 and STAT5 has been shown to contribute to the etiology of certain human cancers and immunodeficiencies." (PMID 35163491, 2022). "As the core gene of the PRAD immune microenvironment, the low expression of LTF in PRAD promotes the occurrence of immunodeficiency, PRAD, and the enrichment of the Janus kinase (JAK)/STAT3 signal pathway." (PMID 34868909, 2021). "The STAT3 variant was also found in heterozygosity in her mother (I:2) and her brother (II:4) who were both asymptomatic, had low HIES score and no history suggestive of HIES, STAT3 GOF or any other immunodeficiency condition." (PMID 39928202, 2025). "Exome sequencing revealed two homozygous hypomorphic mutations affecting the pseudo-kinase domain of JAK1 leading to impaired phosphorylation of several STAT proteins (STAT1, STAT3, STAT4, STAT5, and STAT6), which contributed to the immunodeficiency manifested by the patient." (PMID 41438753, 2025). "Notably, from the PPI network, we observed that TNF, STAT3, TLR4, PIK3R1, and HSP90AB1 were significant targets for GAC intervention in CY-induced immunodeficiency." (PMID 37853057, 2023). "This suggests that the TNF and STAT3 genes are likely to be crucial in the development of CY-induced immunodeficiency, and targeting them could be a potential therapeutic approach for GAC in treating immunodeficiency." (PMID 37853057, 2023). "Patients with atopic dermatitis were chosen as a comparison group for the patients with AD-HIES since they were similarly seen at NIH, were also characterized by S. aureus skin colonization and infection, but did not have the dysfunctional STAT3-dependent immunodeficiency that defines AD-HIES." (PMID 28587312, 2017). "As expected, our study identified several well-known PADs such as STAT3, WAS, DOCK8, SPINK5, and CARD11 that are classified according to the IUIS as combined immunodeficiency with or without syndromic features." (PMID 35273610, 2022). "A recent overview of patients with STAT3 GOF describes the general phenotype of the patients, including autoimmune cytopenias, lymphadenopathy, enteropathy, and interstitial lung disease, while immunodeficiency is not predominant." (PMID 32047491, 2019).
diffuse large B-cell lymphoma (88 papers, 2011 to 2026). "In this study we analyzed the STAT3 polymorphisms and prognosis of 166 diffuse large B-cell lymphoma (DLBCL) patients who were treated with rituximab from 2007 to 2010." (PMID 24624997, 2014). "Recently, a M206K mutation that localizes in the coiled-coil domain of STAT3 was discovered in diffuse large B cell lymphoma, and this mutation was demonstrated to enhance both the STAT3Y705 phosphorylation and its transcriptional activity." (PMID 24995504, 2014). "In particular, overactive STAT3 is frequently found in diffuse large B-cell lymphoma (DLBCL) and is associated with poorer outcomes." (PMID 24142927, 2013). "To summarize, AnnoMiner’s peak integration function was able to identify genes directly associated with ABC-type diffuse large B-cell lymphomas and potential direct targets for the transcription factor STAT3 by using a single user interface and a single AnnoMiner analysis step." (PMID 34326396, 2021). "In diffuse large B-cell lymphoma (DLBCL), the transcription factor STAT3 has been associated with aggressive disease phenotype and worse overall survival." (PMID 30446007, 2018). "Overexpression of HDAC3 in diffuse large B-cell lymphoma (DLBCL) interferences with STAT3 and causes increased expression of it." (PMID 26865932, 2015). "Concentration-dependent inhibition of IL-23–induced STAT3 phosphorylation by JNJ-77242113 in human diffuse large-cell B-lymphoma (DB) cells was investigated at different concentrations of IL-23 to determine the mode of inhibition." (PMID 39080319, 2024). "AZD9150, an ASO drug targeting STAT3, was validated as effective in patients with diffuse large B-cell lymphoma assessed in a phase 1b clinical trial." (PMID 38184597, 2024). "Research in diffuse large B-cell lymphoma highlights the direct regulation of ARHGEF2 by STAT3 in enhancement of cell migration." (PMID 39456519, 2024). "ART exhibits cytotoxic effects in primary effusion lymphoma and induces apoptosis, autophagy and ferroptosis in diffuse large B cell lymphoma cells by impairing STAT3 signaling." (PMID 39525639, 2024). "Thieno [2,3-b]quinoline-procaine hybrid 4 can directly activate SHP1 and inhibit activated B-cell-like diffuse large B-cell lymphoma (ABC-DLBCL) cell proliferation via blocking the STAT3 pathway." (PMID 36985458, 2023). "In diffuse large B-cell lymphoma (DLBC), a study has shown that the mutation of STAT3 induces the occurrence of this cancer." (PMID 36977736, 2023). "In tumor cells, S1PR1 was identified as a potential target to block STAT3 signaling in activated B cell-like diffuse large B-cell lymphoma." (PMID 36361531, 2022). "OPB‐111077, another novel inhibitor of STAT3, also exhibits promising anti-cancer activity in patients with diffuse large B‐cell lymphoma (DLBCL) and modest efficacy was observed against other tumors, including GC, when given as a monotherapy." (PMID 35844493, 2022). "STAT3 also induces chemoresistance in diffuse large B-cell lymphomas through a decreased expression of Casp8, among many other genes." (PMID 33557010, 2021). "STAT3 is the target of ferroptosis in cancer cells, and impaired STAT3 signaling induces ferroptosis in diffuse large B-cell lymphoma cells." (PMID 34869304, 2021). "The BCR is also able to induce the IL-10/STAT3 signaling with increased expression of PD-L1 in diffuse large B-cell lymphoma." (PMID 31382969, 2019). "Recently, Yao and coauthors reported a tight interaction of Fbw7 and STAT3 in activated B-cell-like diffuse large B cell lymphoma (ABC-DLBCL)." (PMID 29914167, 2018). "High levels of phosphorylated Stat3 (pStat3) protein were found in diffuse large B-cell lymphoma, while data on the expression of Stat3 in PCNSL are controversial." (PMID 28415725, 2017). "Previous findings indicate that STAT3 up-regulates c-Myc expression in IL21-treated diffuse large B-cell lymphoma." (PMID 26305332, 2015).